FOXA2 (forkhead box A2)
Description:
Transcription factor that is involved in embryonic development, establishment of tissue-specific gene expression and regulation of gene expression in differentiated tissues. Is thought to act as a 'pioneer' factor opening the compacted chromatin for other proteins through interactions with nucleosomal core histones and thereby replacing linker histones at target enhancer and/or promoter sites. Binds DNA with the consensus sequence 5'- [AC]A[AT]T[AG]TT[GT][AG][CT]T[CT]-3' (By similarity). In embryonic development is required for notochord formation. Involved in the development of multiple endoderm-derived organ systems such as the liver, pancreas and lungs; FOXA1 and FOXA2 seem to have at least in part redundant roles. Originally described as a transcription activator for a number of liver genes such as AFP, albumin, tyrosine aminotransferase, PEPCK, etc. Interacts with the cis-acting regulatory regions of these genes. Involved in glucose homeostasis; regulates the expression of genes important for glucose sensing in pancreatic beta-cells and glucose homeostasis. Involved in regulation of fat metabolism. Binds to fibrinogen beta promoter and is involved in IL6-induced fibrinogen beta transcriptional activation.
Synonyms: HNF-3-beta; HNF3B; TCF3B
Tractability: No criterion of Open Targets' tractability assessment is met for any kind of drug.
Safety:
Unwanted effects reported when the protein is acted on. In parentheses: how it was acted on, where the effect was seen, and who reports it.
Increased, Liver Steatosis (inhibition; source: AOP-Wiki)
Gene: Protein-coding gene on chromosome 20 (22,580,998 to 22,585,455, reverse strand). Ensembl gene ENSG00000125798.
Subcellular location: Nucleus; Cytoplasm
Subcellular location (Human Protein Atlas): Cell Junctions; Nucleoplasm
Pathways (Reactome):
Developmental Biology: Developmental Lineage of Multipotent Pancreatic Progenitor Cells; Developmental Lineage of Pancreatic Acinar Cells; Developmental Lineage of Pancreatic Ductal Cells; Formation of axial mesoderm; Formation of definitive endoderm; Regulation of gene expression in beta cells
Cell-Cell communication: Positive Regulation of CDH1 Gene Transcription
Gene Ontology:
Molecular function: DNA binding; DNA-binding transcription factor activity; nucleic acid binding; sequence-specific double-stranded DNA binding; transcription cis-regulatory region binding; DNA-binding transcription activator activity, RNA polymerase II-specific; DNA-binding transcription factor activity, RNA polymerase II-specific; DNA-binding transcription repressor activity, RNA polymerase II-specific; RNA polymerase II cis-regulatory region sequence-specific DNA binding; RNA polymerase II-specific DNA-binding transcription factor binding; transcription corepressor activity; protein domain specific binding; sequence-specific DNA binding
Biological process: dopaminergic neuron differentiation; endocrine pancreas development; negative regulation of epithelial to mesenchymal transition; negative regulation of ferroptosis; positive regulation of DNA-templated transcription; positive regulation of transcription by RNA polymerase II; regulation of blood coagulation; regulation of transcription by RNA polymerase II; adult locomotory behavior; anatomical structure morphogenesis; cell differentiation; cell fate specification; negative regulation of transcription by RNA polymerase II; positive regulation of cell-cell adhesion mediated by cadherin; positive regulation of embryonic development; positive regulation of gastrulation; primitive streak formation; regulation of insulin secretion involved in cellular response to glucose stimulus; response to interleukin-6; regulation of DNA-templated transcription
Cellular component: nucleoplasm; nucleus; chromatin; cytoplasm
Genetic constraint (gnomAD): Loss-of-function variants: 9 observed, 30.33 expected, observed/expected ratio (o/e) 0.3, 90% interval 0.18 to 0.52. The upper end of that interval is the gene's LOEUF score, 0.52, which puts it in group 2 of 6, group 1 being the genes least tolerant of losing a copy. Missense variants: 686 observed, 623.12 expected, observed/expected ratio (o/e) 1.1, 90% interval 1.03 to 1.17. Synonymous variants: 320 observed, 272.53 expected, observed/expected ratio (o/e) 1.17, 90% interval 1.07 to 1.29.
Gene-disease validity (ClinGen):
ClinGen rates the evidence that FOXA2 causes each of these diseases.
combined pituitary hormone deficiencies, genetic form (autosomal dominant): Moderate.
Homologues: Orthologues: chimpanzee FOXA2 (99% identical), macaque FOXA2 (98% identical), dog FOXA2 (98% identical), mouse Foxa2 (97% identical), pig FOXA2 (97% identical), rabbit FOXA2 (96% identical), rat Foxa2 (95% identical), guinea pig FOXA2 (94% identical), tropical clawed frog foxa2 (67% identical), zebrafish foxa2 (65% identical), Drosophila melanogaster fkh (41% identical), Caenorhabditis elegans pha-4 (33% identical). Paralogues in human: FOXA1 (57% identical), FOXA3 (38% identical), FOXC2 (24% identical), FOXC1 (23% identical), FOXD2 (22% identical), FOXB1 (22% identical), FOXD1 (21% identical), FOXE1 (21% identical), FOXJ3 (21% identical), FOXB2 (20% identical), FOXI3 (20% identical), FOXE3 (20% identical), and 29 more.
Diseases named in the same sentence as FOXA2 in open-access papers:
FOXA2 is named in the same sentence as 173 diseases in open-access papers, as found by Europe PMC text mining. Sharing a sentence is not in itself a finding about the gene and the disease. The quoted sentences say what the papers report.
lung carcinoma (43 papers, 2008 to 2025). "High expressions of FoxA1 and FoxA3 in lung cancer were related with poor overall survival, whereas FoxA2 overexpression was associated with a better overall survival, suggesting the opposing roles between FoxA1/A3 and FoxA2 in the carcinogenesis." (PMID 32151057, 2020). "FOXA2 regulates the expression of genes critical to lung morphogenesis, and loss of FOXA2 expression is frequent in lung cancer cell lines." (PMID 29456509, 2018). "More importantly, when the expression of LINC00261/FOXA2 transcripts were correlated with the experimentally verified group of fast and slow migrating lung cancer cell lines, higher expression was evidently associated with the slow migrating cell line panel." (PMID 30597925, 2018). "Other studies showed that aberrant DNA methylation was associated with dysregulation of SPDEF and FOXA2 expression in lung cancer, although DNA methylation regulation of SPDEF and FOXA2 expression has not been assessed in lung tissue of patients with COPD." (PMID 28450970, 2017). "Loss of FOXA2 expression was found frequent in lung cancer cell lines and NSCLC tumor samples." (PMID 34827193, 2021). "To monitor whether this association of the LINC00261/FOXA2 locus with epithelial cells and epithelial markers was a broadly conserved process in lung cancer, we further employed a sophisticated bioinformatic analysis." (PMID 30597925, 2018). "Furthermore, higher expression of the LINC00261/FOXA2 locus was associated with lung cancer cell lines with lower migratory capacity." (PMID 30597925, 2018). "Hierarchical clustering of gene expression data from lung cancer cell lines could further verify the association of high LINC00261/FOXA2 expression to an epithelial gene signature." (PMID 30597925, 2018). "GABA transaminase deficiency caused by a mutation of Abat leads to neonatal epilepsy, while activation through the FOXA2/ABAT/GABA axis mediates the development of brain metastasis in lung cancer." (PMID 40699779, 2025). "Our findings indicate that lung cancer cells can activate the NF-κB pathway via the FOXA2/ABAT/GABA axis, thereby facilitating brain metastasis." (PMID 39972344, 2025). "In lung cancer, FOXA2 has been reported to be downregulated and inhibits lung cancer cell proliferation and metastasis." (PMID 36289750, 2022). "In this study, we first systematically analyzed the expression of eight AT II-associated genes (AQP4, SFTPB, SFTPC, SFTPD, CLDN18, FOXA2, NKX2-1, and PGC) in lung cancer." (PMID 36203529, 2022). "In this study, we comprehensively analyzed the gene expression, prognosis value, genetic alteration, and immune cell infiltration of eight AT II-associated genes (AQP4, SFTPB, SFTPC, SFTPD, CLDN18, FOXA2, NKX2-1, and PGC) in Nonsmall Cell Lung Cancer (NSCLC)." (PMID 36203529, 2022). "For instance, it has been reported that downregulation of FOXA2 promoted the ability of migration and invasion in lung cancer." (PMID 34551777, 2021). "FTX overexpression activated FOXA2 expression, while transfection of miR‐200a‐3p mimics inhibited FOXA2 expression in lung cancer cells." (PMID 32176463, 2020). "These suggested that FoxA3 plays oncogenic function in lung cancer and esophageal cancer via elevation of FoxA1 and FoxA2 expressions." (PMID 32151057, 2020). "FOXA2 is a transcriptional regulator which has a critical impact on lung cancer cell growth and metastasis." (PMID 32176463, 2020). "These collecting data demonstrate that FTX acts as a sponge of miR‐200a‐3p to activate FOXA2 expression in lung cancer cells." (PMID 32176463, 2020). "Control of FOXA2 expression by LINC00261 has also been observed in lung cancer cells and mouse hepatocytes." (PMID 32414223, 2020).
lung carcinoma (continued). "All these data establish LINC00261 and FOXA2 as an epithelial-specific marker pair, downregulated during EMT and lung cancer progression, and associated with lower cell migration potential in lung cancer cells." (PMID 30597925, 2018). "Our data provides an important basis for future investigations on the role of the LINC00261/FOXA2 axis in lung cancer tumorigenesis, progression and metastasis to characterize their tumor suppressive and anti-metastatic functions in lung cancer." (PMID 30597925, 2018). "Lastly, when the genes for NKX2-1, FoxA1 and FoxA2 were deleted later, in lung tumors that had already formed, the outcome was a more aggressive type of lung cancer that also occurs in human patients." (PMID 30475207, 2018). "Consistent with the co-expression of LINC00261/FOXA2 in lung cancer samples, TGFβ1 also induced a significant suppression of FOXA2." (PMID 30597925, 2018). "Conversely, FOXA2 also is downregulated in lung cancer through epigenetic silencing of hypermethylation." (PMID 28852427, 2017). "FOXA2 was shown to be repressed and hypermethylated in its promoter in lung cancer, whereas it was also shown that FOXA2 was activated with hypermethylation in the promoter during endoderm development." (PMID 28450970, 2017). "The HNF3β/FoxA2 gene has a CpG island in its promoter; and the region is often methylated in breast and lung cancers prompting us to examine thyroid carcinoma cells." (PMID 18682709, 2008). "A previous study shows that simultaneous knockouts of Nkx2.1, FoxA1 and FoxA2 could induce squamous transition in Kras-driven lung cancer." (PMID 39687207, 2024). "Another studies discovered that FTX could inhibit the proliferation and metastasis of lung cancer cells by activating FOXA2 or could suppress the proliferation of hepatocellular carcinoma cells by impeding DNA replication." (PMID 37106382, 2023). "Studies have shown that FOXA2 could function as a regulator in lung cancer, breast cancer, prostate cancer, bladder cancer, and Barrett’s metaplasia." (PMID 38072043, 2023). "FOXA2 has also been implicated as an EMT antagonist in pancreatic, colon, and lung cancers." (PMID 35703180, 2022). "Interestingly, we observed that linc00261 was significantly down-regulated after treatment with TGF-β1, which is consistent with TGF-β1 induced-suppression of linc00261/Foxa2 in lung cancer cells." (PMID 35123494, 2022). "Furthermore, we demonstrated that FOXA2 was a downstream target of FTX, while rescue experiments indicated that silencing of FOXA2 attenuated the effect of FTX on lung cancer growth and metastasis." (PMID 32176463, 2020). "To test whether FOXA2 is critical for FTX‐mediated inhibition of lung cancer cell growth and metastasis, we silenced FOXA2 expression in FTX‐OE A549 cells to do rescue experiments." (PMID 32176463, 2020). "Furthermore, we find that FTX overexpression activates the expression of transcription factor FOXA2, an important regulator in lung cancer progression, and we reveal a novel FTX/miR‐200a‐3p/FOXA2 competing endogenous RNA regulatory axis in lung cancer cells." (PMID 32176463, 2020). "In summary, our study demonstrates that FTX may function as a tumour suppressor gene and regulate lung cancer development through acting as a sponge of miR‐200a‐3p to promote FOXA2 expression." (PMID 32176463, 2020). "Thus, NKX2-1, FoxA1 and FoxA2 coordinately regulate the growth and identity of lung cancer in a context-specific manner." (PMID 30475207, 2018). "Importantly and consistent with the expression pattern in the primary tumor samples, both genes derived from the LINC00261/FOXA2 locus were strongly downregulated in the fast migrating lung cancer cell lines compared to the slow migrating cell lines." (PMID 30597925, 2018). "Moreover, the down-regulated ENSG00000259974 regulated the target PCG FOXA2 that acted as a suppressor of lung cancer in cis-acting regulation." (PMID 29069717, 2017).
lung carcinoma (continued). "For instance, in lung we found FOXA2, TBX4 and BMP4, and although the role of LHX6 in lung development is less well defined, it has previously been implicated as a tumour suppressor in lung cancer." (PMID 27562343, 2016). "The involvement of ratio of FOXA1 to FOXA2 in lung cancer remains poorly known." (PMID 26658322, 2015). "Interestingly, HNF3β/FoxA2 is a methylated gene in breast and lung cancer cells; and overexpression of HNF3β/FoxA2 in a lung cancer cell line leads to growth arrest and apoptosis." (PMID 18682709, 2008). "Furthermore, we revealed a novel FTX/miR‐200a‐3p/FOXA2 signalling axis in lung cancer progression." (PMID 32176463, 2020). "Studies suggest that FOXA2 may be a suppressor of tumor metastasis in human lung cancers." (PMID 29456509, 2018). "Interestingly, a cohort of these lung cancers showed that only higher expression of FOXA1, not FOXA2, linked with overall survival in all lung cancer, but not in lung ADCs and SCCs (data not shown)." (PMID 26658322, 2015). "Therefore, in lung cancer FOXA1 activity may be regulated by other regulators such as FOXA2 whose activities could be directly modulated through epigenetic mechanisms." (PMID 24093963, 2013). "The expression of ASCL1, FOXA2, and PROX1 positively correlated in prostate cancer patient datasets as well as lung cancer." (PMID 39470735, 2024). "Nkx2-1 and Foxa2 are co-expressed in normal AT2 cells and they can also coordinately regulate lung cancer cell growth and identity in a context-specific manner." (PMID 36993454, 2023). "For example, in several human cell lines, including liver carcinoma (Hep2), lung carcinoma (A540), and ESC-derived endoderm, FOXA2 show cell-type–specific binding: only 6% to 14% of FOXA2 binding occurs in its recognition motifs in the mentioned cell types." (PMID 36358822, 2022). "FOXA2 was reported to inhibit EMT and suppress metastasis in human lung cancer cell lines via repressing the SLUG promoter." (PMID 34827193, 2021). "In lung cancer, FOXA1 and FOXA2 is involved in regulation of Epithelial to Mesenchymal genes relevant to cellular adhesion and cellular communication, and associated with distant metastasis." (PMID 33272232, 2020). "For example, FOXA2 is a tumour suppressor and inhibitor of EMT in human lung cancers and reduced FOXA2 expression in hepatocellular carcinoma (HCC) is associated with worse clinical outcome." (PMID 29540241, 2018). "FOXA2 was involved in the functions including FOXA1 transcription factor network and cell communication, and FOXA2 was downregulated during EMT of lung cancer." (PMID 24093963, 2013). "FTX overexpression inhibited lung cancer cell proliferation and metastasis via interacting with miR‐200a‐3p to promote FOXA2 expression, suggesting that FTX may act as a tumour suppressor in lung cancer progression." (PMID 32176463, 2020). "The result of RNA pull‐down assay suggested that FTX interacted with miR‐200a‐3p in lung cancer cells, and Luciferase Reporter Gene Assay indicated that miR‐200a‐3p could both target FTX and FOXA2 genes." (PMID 32176463, 2020). "Indeed, our results suggest that the core transcriptional regulatory circuitry of A549 lung cancer cells is centered on FOSL2 and FOXA2." (PMID 27739523, 2016). "However, in lung cancer, pancreatic cancer, and colorectal cancer, FOXA2 was downregulated in tumor tissues, when compared to non-tumor tissues." (PMID 34551777, 2021). "While we could see that LINC00261 expression is FOXA2-dependent, the inverse was not true in the lung cancer cell lines tested." (PMID 30597925, 2018). "How FOXA2 participates in lung cancer pathogenesis is not very clear." (PMID 29456509, 2018). "Interestingly, both FOXA2 and FOSL2 are suspected to play major role in lung cancer progression." (PMID 27739523, 2016).
lung carcinoma (continued). "Studies have shown that FOXA2 could function as a tumor suppressor by selectively binding to the promoter of several genes related to epithelial–mesenchymal transition (EMT), such as Slug, CDH1 or Zeb2, to suppress tumor migration and progression in lung cancer, breast cancer or liver cancer." (PMID 38072043, 2023). "However, seven genes selected from FSL (FOXA2, C4BPA, SCGB3A1, DDX58, CCNDBP, TMSB4X, and CXCL17), and one gene selected from both FSL as well as RSL (CD9), were up-regulated in the lung cancer tissues, but not significantly (P > 0.05)." (PMID 23374247, 2013).